EPHA2 (EPH receptor A2)
Description:
Receptor tyrosine kinase which binds promiscuously membrane-bound ephrin-A family ligands residing on adjacent cells, leading to contact-dependent bidirectional signaling into neighboring cells. The signaling pathway downstream of the receptor is referred to as forward signaling while the signaling pathway downstream of the ephrin ligand is referred to as reverse signaling. Activated by the ligand ephrin-A1/EFNA1 regulates migration, integrin-mediated adhesion, proliferation and differentiation of cells. Regulates cell adhesion and differentiation through DSG1/desmoglein-1 and inhibition of the ERK1/ERK2 (MAPK3/MAPK1, respectively) signaling pathway. May also participate in UV radiation-induced apoptosis and have a ligand-independent stimulatory effect on chemotactic cell migration. During development, may function in distinctive aspects of pattern formation and subsequently in development of several fetal tissues. Involved for instance in angiogenesis, in early hindbrain development and epithelial proliferation and branching morphogenesis during mammary gland development. Engaged by the ligand ephrin-A5/EFNA5 may regulate lens fiber cells shape and interactions and be important for lens transparency development and maintenance. With ephrin-A2/EFNA2 may play a role in bone remodeling through regulation of osteoclastogenesis and osteoblastogenesis. (Microbial infection) Acts as a receptor for hepatitis C virus (HCV) in hepatocytes and facilitates its cell entry. Mediates HCV entry by promoting the formation of the CD81-CLDN1 receptor complexes that are essential for HCV entry and by enhancing membrane fusion of cells expressing HCV envelope glycoproteins. Acts as a receptor for human cytomegalovirus (HCMV) to mediate viral entry and fusion in glioblastoma cells.
Synonyms: ECK; ARCC2; CTPA; CTPP1; CTRCT6
Tractability: Small molecule: an approved drug acts on it; a structure with a bound ligand is known; a high-quality ligand is known; it has a high-quality binding pocket; it belongs to a druggable protein family. Antibody: UniProt places it where antibodies can reach, with high confidence; its Gene Ontology location is reachable by antibodies, with high confidence; UniProt predicts a signal peptide or a membrane-spanning region; the Human Protein Atlas places it where antibodies can reach. PROTAC: it is named in the literature on targeted protein degradation; UniProt records ubiquitination sites on it; ubiquitination databases record sites on it; its protein half-life has been measured; a small molecule that binds it is known.
Target class: Tyrosine protein kinase Eph family; Protein Kinase; TK protein kinase group; Kinase; Enzyme
Gene: Protein-coding gene on chromosome 1 (16,124,337 to 16,156,069, reverse strand). Ensembl gene ENSG00000142627.
Subcellular location: Cell membrane; Cell projection, ruffle membrane; Cell projection, lamellipodium membrane; Cell junction, focal adhesion
Subcellular location (Human Protein Atlas): Cell Junctions; Plasma membrane; Golgi apparatus; Nuclear speckles
Pathways (Reactome):
Signal Transduction: RAC1 GTPase cycle; RAC2 GTPase cycle; RAC3 GTPase cycle; RHOG GTPase cycle; RHOU GTPase cycle; RHOV GTPase cycle; RND1 GTPase cycle; RND2 GTPase cycle; RND3 GTPase cycle
Developmental Biology: EPH-Ephrin signaling; EPH-ephrin mediated repulsion of cells; EPHA-mediated growth cone collapse
Gene Ontology:
Molecular function: cadherin binding; ephrin receptor activity; growth factor binding; molecular function activator activity; protein binding; transmembrane receptor protein tyrosine kinase activity; ATP binding; protein kinase activity; protein tyrosine kinase activity
Biological process: cAMP metabolic process; cell chemotaxis; cell migration; cell motility; ephrin receptor signaling pathway; intrinsic apoptotic signaling pathway in response to DNA damage; keratinocyte differentiation; negative regulation of cell adhesion mediated by integrin; positive regulation of bicellular tight junction assembly; positive regulation of cell migration; positive regulation of protein localization to plasma membrane; protein localization to plasma membrane; regulation of ERK1 and ERK2 cascade; regulation of lamellipodium assembly; response to growth factor; angiogenesis; bone remodeling; branching involved in mammary gland duct morphogenesis; cell surface receptor protein tyrosine kinase signaling pathway; lens fiber cell morphogenesis; mammary gland epithelial cell proliferation; osteoblast differentiation; osteoclast differentiation; regulation of angiogenesis; regulation of blood vessel endothelial cell migration; and 5 more
Cellular component: cell junction; cell surface; focal adhesion; lamellipodium; leading edge membrane; plasma membrane; tight junction; receptor complex; lamellipodium membrane; membrane; ruffle membrane
Genetic constraint (gnomAD): Loss-of-function variants: 54 observed, 103.92 expected, observed/expected ratio (o/e) 0.52, 90% interval 0.42 to 0.65. The upper end of that interval is the gene's LOEUF score, 0.65, which puts it in group 2 of 6, group 1 being the genes least tolerant of losing a copy. Missense variants: 1,117 observed, 1,389.2 expected, observed/expected ratio (o/e) 0.8, 90% interval 0.76 to 0.85. Synonymous variants: 560 observed, 569.36 expected, observed/expected ratio (o/e) 0.98, 90% interval 0.92 to 1.05.
Homologues: Orthologues: chimpanzee EPHA2 (99% identical), macaque EPHA2 (98% identical), rabbit EPHA2 (95% identical), pig EPHA2 (95% identical), mouse Epha2 (93% identical), rat Epha2 (93% identical), guinea pig EPHA2 (92% identical), dog EPHA2 (91% identical), tropical clawed frog epha2 (72% identical). Paralogues in human: EPHA5 (53% identical), EPHA4 (51% identical), EPHA7 (51% identical), EPHA3 (51% identical), EPHA6 (50% identical), EPHB2 (49% identical), EPHA1 (48% identical), EPHB1 (48% identical), EPHB3 (48% identical), EPHA8 (48% identical), EPHB4 (45% identical), EPHA10 (41% identical), and 41 more.
Diseases named in the same sentence as EPHA2 in open-access papers:
EPHA2 is named in the same sentence as 268 diseases in open-access papers, as found by Europe PMC text mining. Sharing a sentence is not in itself a finding about the gene and the disease. The quoted sentences say what the papers report.
breast cancer (128 papers, 2007 to 2025). A primary or metastatic malignant neoplasm involving the breast. "E-cadherin plays a role in regulating the cell surface localization of EphA2 in breast cancer cells, and the loss of cell–cell contacts can impede interaction with ephrin ligands, making Eph receptor oncogenic activity appear to be ligand independent." (PMID 38811954, 2024). "For example, a cell-associated EPHA2 ∼60 kDa fragment generated by MMP14-mediated cleavage in the FN1 domain has been implicated in breast cancer cell invasiveness through S897 phosphorylation." (PMID 39706267, 2024). "In breast cancer, EphA2 overexpression is associated with the most aggressive triple-negative breast cancer subtype." (PMID 37046604, 2023). "EphA2 overexpression in breast cancer is associated with poor prognosis and has been implicated in mechanisms of resistance to EGFR family inhibitors, as recently reviewed." (PMID 36830852, 2023). "High levels of EPHA2 in circulating exosomes are associated with cancer progression and suggest poor clinical outcomes in breast cancer patients." (PMID 35673569, 2022). "In non-small cell lung cancer and breast cancer, overexpression of EPHA2 correlated to tumorigenesis and risk of metastasis." (PMID 35008410, 2022). "The upregulation of EPHA2 is associated with poor prognosis, increased metastatic potential and reduced survival in breast cancer patients 23-26." (PMID 35673569, 2022). "Ephrin type-A receptor 2 (EPHA2) is a receptor tyrosine kinase (RTK), the overexpression of EPHA2 is associated with metastasis in a variety of cancers, including melanomas and ovarian, prostate, lung, and breast cancers." (PMID 34490085, 2021). "In support of this, expression of kinase-deficient variants of EphA2 in breast cancer cells led to decreased tumor volume and increased tumor cell apoptosis." (PMID 33572284, 2021). "Aberrant expression of EphA2 has been associated with many human malignancies, such as lung cancer, breast cancer, ovary cancer, esophageal cancer, colorectal cancer, glioblastoma, and melanoma." (PMID 34221956, 2021). "In this study, the potential role of EphA2 in this clinically relevant phenomenon is investigated as metastasis of breast cancer to bone is a major cause of morbidity and mortality in patients." (PMID 33869989, 2021). "In conclusion, this study reveals a novel function for EphA2 signaling in tumor cell–bone cell interactions involved in osteoclastogenesis and osteolysis associated with breast cancer metastasis, in part through regulation of cytokines such as IL‐6." (PMID 33869989, 2021). "While EphA2 has been well characterised in the oncogenesis of breast cancer, its association with lesser prevalent cancers such as KS is still being elucidated." (PMID 33430066, 2021). "Several studies have linked EphA2 function to breast tumor growth and visceral metastasis in multiple breast cancer subtypes, including HER2+24 and basal‐like, triple‐negative models." (PMID 33869989, 2021). "Since elevated EphA2 expression is correlated with the aggressiveness of breast cancer, Ephexin4 links EphA2 to RhoG causing cancer invasion." (PMID 30682817, 2019). "In contrast to our experimental work that was performed in breast cancer and glioblastoma cell lines, we used another cancer type, colorectal cancer, to demonstrate the association between TF and EphA2 in human tumor tissue." (PMID 27246245, 2016). "We did prioritize EPHA2 as a driver in breast cancer, despite its relatively low number of mutations." (PMID 27808240, 2016). "EphA2 overexpression is often accompanied by loss of expression or mislocalization of ephrin-A1 in breast cancer, glioma and skin tumors." (PMID 22916121, 2012). "Preclinical testing of possible combination therapies will also benefit from study of these mouse models to determine the effects of Eph expression and targeting on sensitisation to established therapies, as seen with trastuzumab resistance associated with EphA2 in HER2-positive breast cancer." (PMID 36830852, 2023).
breast cancer (continued). "Apart from breast cancer, EPHA2 overexpression has also been associated with poor prognosis in several other types of malignant tumors including ovarian, cervical, colorectal, vulvar, gastric, lung, oral, endometrial, esophageal, renal cell carcinomas, and gliomas." (PMID 35204461, 2022). "Exosomal EPHA2 has also been linked to promoting breast cancer metastasis." (PMID 35408909, 2022). "As already mentioned in the context of breast cancer, this could be due to low ephrin expression, an impaired EphA2-ephrin-A1 interaction due to loss of cadherin, or dephosphorylation of Tyr772 by LMW-PTP." (PMID 33430066, 2021). "Similar to EphA2, EphB4 has been implicated in breast cancer in numerous studies." (PMID 33430066, 2021). "Furthermore, our data provide preclinical support for targeting EphA2 in advanced‐stage breast cancer disease associated with bone metastasis to disrupt the vicious cycle." (PMID 33869989, 2021). "Immunohistochemical staining for EphA2, using an antibody validated in human tumor samples and in EphA2‐deficient mice, was performed in a set samples from de‐identified patients with human breast cancer bone metastases (generously provided by Dr Conor Lynch)." (PMID 33869989, 2021). "Considering the rounded collagen invasive phenotype of OCKI_p03 and OCKI_p06 cells, resembling the reported EphA2‐dependent breast cancer cell phenotypes, and EphA2 association with OC clinical outcome, we analyzed EphA2 in these ex vivo cultures by immunofluorescence." (PMID 32115889, 2020). "EphA2 has been reported to be associated with cancer stem-cell qualities, and to promote tumor neo-angiogenesis, and metastasis, including cross-talk with erbB receptor signaling to control initiation and spread of erbB2-dependent mammary tumors in mice." (PMID 32397088, 2020). "Interestingly, enhanced EphA2 expression in human breast cancer is associated with a poor patient prognosis." (PMID 24705208, 2013). "Notably, they highlighted that measuring the accompanying ephrins’ expression might have clinical significance by reporting the loss of ephrin-A1 expression in EPHA2-positive breast cancer tissues accompanied by lymph node metastasis." (PMID 35204461, 2022). "Thus, it is tempting to speculate that EphA2 overexpression in breast cancer might be linked to the loss of hormone dependence that frequently arises in advanced stages of the disease." (PMID 32811512, 2020). "As an RTK, EphA2 plays critical roles in cellular functions and is recognized as a promising therapeutic target in multiple cancers, including breast cancer." (PMID 41130297, 2025). "By elucidating the role of EPHA2 and its interaction with key signaling pathways, this study paves the way for potential therapeutic strategies targeting these mechanisms in breast cancer." (PMID 40919148, 2025). "They evaluated the binding potency, cytotoxic effects, apoptosis induction capacity, and internalization of the designed immunotoxin on an EphA2-overexpressing breast cancer cell line." (PMID 40718433, 2025). "Abundant expression of EphA2 has been reported in various cancers, such as prostate, lung, esophageal, colorectal, cervical, ovarian, skin, and breast cancers." (PMID 40236294, 2025). "Peptide-based agents like [18F]AFP-SWL, [99mTc]-HYNIC-SWL, and [68Ga]DOTA-SD01 have shown specificity for EphA2 in melanoma, non-small cell lung, and breast cancers, but issues with plasma degradation and low tumor uptake have limited their use 22-24." (PMID 40225586, 2025). "The results indicated that the TNBC-associated cell line MDA-MB-231 exhibited the highest levels of EPHA2 expression, while lower levels were observed in other breast cancer subtypes." (PMID 40919148, 2025). "recently found that exosomes produced by high metastatic potential breast cancer cells are rich in EPHA2, which can promote angiogenesis and metastasis via AMPK signaling." (PMID 40249328, 2025).
breast cancer (continued). "Recent findings highlight the functional role of drug resistant-derived exosomal EphA2 in promoting the transmission of an aggressive phenotype and metastasis between breast cancer cells and other cellular components." (PMID 38473244, 2024). "In breast cancer, EphA2 overexpression was exploited to more precisely deliver the therapeutic agent DOX using mesoporous silica nanoparticles (MSNs) modified with the YSA peptide recognizing EphA2." (PMID 39596256, 2024). "Ephrin type-A receptor 2 (EPHA2) is a receptor tyrosine kinase that is overexpressed in a variety of cancers, including breast cancer." (PMID 38855323, 2024). "In the context of HER2-positive breast cancer, the receptor tyrosine kinase EphA2 has been found to promote glutamine metabolism by activating the transcriptional coactivators YAP and TAZ, suggesting potential therapeutic targets in this cancer subtype." (PMID 39408832, 2024). "These nanoparticles increased therapeutic efficacy with low toxicity in EphA2-overexpressing breast cancer cells." (PMID 39596256, 2024). "Dual targeting of both EPHA2 and ER has also been proposed for restoring tamoxifen sensitivity in ER/EPHA2-positive breast cancer." (PMID 38582811, 2024). "For instance, EphA2, expressed at minimal levels in normal human breast epithelium, is significantly overexpressed in 60% to 80% of breast cancers." (PMID 38811954, 2024). "Increased EphA2 protein expression in drug-resistant cancer cell-derived exosomes serves as a potential prognostic marker for drug resistance-induced breast cancer progression." (PMID 38473244, 2024). "The signaling pathway involving EphA2 and ephrin A1 is aberrantly regulated in various tumor entities, particularly in breast cancer." (PMID 38612592, 2024). "This agrees with results of a previous study demonstrating that overexpression of EPHA2 can decrease estrogen dependence and tamoxifen sensitivity of the breast cancer cell line MCF7." (PMID 38582811, 2024). "This study reports for the first time that LINC02086 modulates EPHA2 expression throughmiR-6757-5p in breast cancer." (PMID 38008720, 2023). "It is the largest group among tyrosine kinase receptor families, and among them, EphA2 is commonly overexpressed in breast cancer." (PMID 37513835, 2023). "Given that EphA2 can interact with HER2 (also named ErbB2) and cooperate with HER2 to activate ERK signaling, we concluded that RNF5 inhibition decreases ERK and Akt activation through the increase in the EphA2 level in HER2-negative breast cancer cells." (PMID 37816703, 2023). "EphA2 and EphB4 have been the most extensively studied in relation to breast cancer, although other Eph receptors have also been identified." (PMID 36830852, 2023). "In conclusion, our study provides in vivo and in vitro evidences that LINC02086 acts as a tumor-promoter, enhancing cell viability and suppressing cell apoptosis in breast cancer through the regulation ofmiR-6757-5p/EPHA2 axis." (PMID 38008720, 2023). "A recent study reveals that Twist1 regulates EPHA2 expression thereby influencing tumor growth and metastasis in basal-like breast cancer." (PMID 38008720, 2023). "RNF5 expression is inversely correlated with EphA2 expression in breast cancers, and a high EphA2 level accompanied by a low RNF5 level is related to better survival in patients with ER-positive, HER2-negative breast cancers." (PMID 37816703, 2023). "Breast cancer overexpressed EphA2-conjugated PGS and PTX encapsulated microspheres have shown increased efficiency in the treatment of breast cancer due to their specificity and overexpression on the surfaces of TNBC." (PMID 37530973, 2023). "Overexpression of EphA2 receptors has been correlated with low survival in all patients with breast cancer subtypes due to the EphA2 activity that enhances tumorigenesis and the progression of metastases." (PMID 37513835, 2023).